TMEM212 (transmembrane protein 212)
Synonyms: FLJ23172
Tractability: Antibody: UniProt predicts a signal peptide or a membrane-spanning region.
Gene: Protein-coding gene on chromosome 3 (171,843,349 to 171,938,715, forward strand). Ensembl gene ENSG00000186329.
Subcellular location: Membrane
Subcellular location (Human Protein Atlas): Endoplasmic reticulum; Nucleoli fibrillar center
Gene Ontology:
Cellular component: membrane
Genetic constraint (gnomAD): Loss-of-function variants: 22 observed, 19 expected, observed/expected ratio (o/e) 1.16, 90% interval 0.83 to 1.64. The upper end of that interval is the gene's LOEUF score, 1.64, which puts it in group 6 of 6, group 1 being the genes least tolerant of losing a copy. Missense variants: 201 observed, 216.59 expected, observed/expected ratio (o/e) 0.93, 90% interval 0.83 to 1.04. Synonymous variants: 74 observed, 83.36 expected, observed/expected ratio (o/e) 0.89, 90% interval 0.74 to 1.08.
Homologues: Orthologues: chimpanzee TMEM212 (99% identical), macaque TMEM212 (96% identical), rabbit TMEM212 (80% identical), pig TMEM212 (79% identical), guinea pig TMEM212 (76% identical), dog TMEM212 (75% identical), rat Tmem212 (75% identical), mouse Tmem212 (74% identical), tropical clawed frog tmem212 (49% identical). Paralogues in human: MS4A4A (19% identical), MS4A7 (17% identical), MS4A12 (16% identical), MS4A5 (16% identical), MS4A8 (15% identical), MS4A15 (14% identical), MS4A3 (14% identical), MS4A6A (14% identical), MS4A2 (14% identical), MS4A18 (13% identical), MS4A4E (13% identical), MS4A1 (13% identical), and 4 more.
Diseases named in the same sentence as TMEM212 in open-access papers:
TMEM212 is named in the same sentence as 1 disease in open-access papers, as found by Europe PMC text mining. Sharing a sentence is not in itself a finding about the gene and the disease. The quoted sentences say what the papers report.
gliosarcoma (1 paper, 2019). A rare histological variant of glioblastoma (WHO grade IV) characterized by a biphasic tissue pattern with alternating areas displaying glial and mesenchymal differentiation (WHO). "Several mRNAs: MLYCD, CFAP54, ATP9B, and TMEM212 were significantly downregulated in gliosarcomas when compared to GBMs." (PMID 30818875, 2019).